MDK (midkine)
Diseases named in the same sentence as MDK in open-access papers (continued):
Sharing a sentence is not in itself a finding about the gene and the disease.
tumor (continued). "It has been demonstrating that the interaction between MDK and its receptor Lrp1 is significantly positively correlated with the infiltration of M2 macrophages in the tumor microenvironment, while negatively correlated with the infiltration of M1 macrophages." (PMID 41276912, 2026). "The animals treated with PBS showed hardly detectable tumor infiltration of CD8+ T cells, and the MDK-siRNA treatment only slightly increased the tumor infiltration of CD8+ T cells." (PMID 40380202, 2025). "The integration of these omics data provides robust molecular validation of MDK’s involvement in tumor progression and underscores its relevance as a candidate for precision oncology." (PMID 40500394, 2025). "MDK modifies the function of several components of the immune system, and recent research shows that blocking MDK can rewire immune cells to resume attack on the tumor." (PMID 41463631, 2025). "MDK expressed by tumor cells can promote enhanced Treg infiltration by promoting Treg motility, with syndecan 4 (SDC4) serving as the putative receptor for MDK on Treg cells." (PMID 40429950, 2025). "Using single-cell and spatial transcriptomic analyses, MDK-NCL communication between tumor cells and other cells was identified as a critical mechanism in shaping the TME." (PMID 40396179, 2025). "In primary NB masses, tumor cells predominantly released midkine (MK), a heparin-binding growth factor that enhances tumor cell growth, survival, metastasis, and angiogenesis, to neighboring neuroblasts, Schwann cells, and endothelial cells." (PMID 41279557, 2025). "Through spatial transcriptomic data, we further revealed the differential spatial distribution of MDK-NCL signaling across various tumor niches." (PMID 40396179, 2025). "In the subsequent receptor-ligand visualization analysis, we found that the MDK-related pathway was particularly prominent, functioning as a ligand interacting with tumor cells." (PMID 40616092, 2025). "As a secreted cytokine, MDK is detectable in biological fluids such as blood, urine, cerebrospinal fluid, or tumor-derived mRNA, making it a cost-effective tool for early diagnosis and prognostic evaluation." (PMID 40500394, 2025). "In summary, our analysis identifies the high enrichment of MDK-NCL in HGSOC tumor cell communication, and subsequent experiments validate that the overexpression of NCL indeed promotes HGSOC tumor cell proliferation through the activation of the AKT pathway." (PMID 40036264, 2025). "Immunofluorescence assay demonstrated that the protein content of Midkine (MDK), one of the top DEGs from these two footprints, increased in Tumor#1 compared to Para#1; however, MDK protein content decreased in Tumor#2 compared to Para#2." (PMID 39540244, 2025). "In the high‐MDK expression group, s‐MDK levels significantly decreased following tumor response and increased during tumor progression." (PMID 40620228, 2025). "Further research utilizing an increased number of tumor samples is evidently required to establish MDK’s utility as a biomarker either alone or in combination with other established biomarkers." (PMID 40429950, 2025). "These tumor subtypes cooperatively drive CD8+ T cell exhaustion through the MDK–(ITGA4+ITGB1), MIF–(CD74+CXCR4), and TGF-β signaling pathways." (PMID 40948762, 2025). "The result showed that MDK was the most significant candidate ligand interacting with PTPRZ1 among tumor cells, consistent with their co‐expression patterns." (PMID 40899632, 2025). "Midkine (MDK) drives tumor aggressiveness and therapeutic resistance by engaging multiple molecular mechanisms." (PMID 40500394, 2025). "We have developed an innovative tumor-specific nanocarrier for the co-delivery of aPD-1 and MDK-siRNA." (PMID 40380202, 2025). "Spatial transcriptomic localisation revealed enrichment of MDK–NCL at the tumor–stroma interface, suggesting a role in mediating immunosuppression." (PMID 41249133, 2025).
tumor (continued). "We discovered and validated the interaction between MDK and c‐Myc and found that ACT001 can target the MDK/c‐Myc complex to inhibit tumour proliferation and growth." (PMID 40468625, 2025). "The convergence of these receptor-mediated pathways underscores MDK’s central role in modulating tumor microenvironment and therapeutic resistance, highlighting its potential as both a biomarker and a target for intervention." (PMID 40500394, 2025). "The expression data indicates that malignant cells, indeed, are the predominant source of MDK in the tumor microenvironment." (PMID 40835683, 2025). "Functionally, GBM-derived MDK induced macrophages to secrete multiple cytokines and chemokines, suggesting its role in reshaping the tumor microenvironment." (PMID 40835683, 2025). "Spatial transcriptomic analysis further implicates midkine (MDK) as the ligand activating PTPRZ1 in LUSC tumor tissue." (PMID 40899632, 2025). "In the context of malignancy, there is substantial evidence for MDK promoting tumor growth and survival by enhancing access to vasculature." (PMID 40429950, 2025). "High communication between C0 TSPAN1+ tumor EPCs and fibroblasts was observed with the MDK-NCL and MDK-LRP1 ligand-receptor pairs, and a chord diagram further validated these interactions." (PMID 40777026, 2025). "MDK is highly expressed in various types of cancer, and it plays a critical role in the tumour microenvironment by promoting tumour cell proliferation, invasion, metastasis, and angiogenesis, as well as exerting anti‐apoptotic effects." (PMID 40468625, 2025). "Our current study identifies the MDK-NCL signaling axis as a central mediator in the interaction between High_FAM49B_EP and tumor-associated macrophages (TAMs)." (PMID 41246334, 2025). "The ability of MDK to suppress cell death is another likely contributing factor to the cytokine’s ability to promote tumor growth." (PMID 40429950, 2025). "The interaction between MDK‐high tumor cells and SPP1+ macrophages has been identified as the key mechanism contributing to the immunosuppressive TME." (PMID 41176774, 2025). "MDK can promote proliferation of various members of the tumor environment, including endothelial cells and cancer-associated fibroblasts." (PMID 40429950, 2025). "Mechanistically, PTPRZ1 mediates MDK‐induced PI3K phosphorylation that is essential for LUSC tumor growth." (PMID 40899632, 2025). "MDK is known to modulate the tumor microenvironment by influencing the survival and recruitment of immune cells, cytokine secretion, and angiogenesis." (PMID 40429950, 2025). "The small molecule inhibitor iMDK has demonstrated strong tumor suppressive activity in preclinical models by directly blocking MDK-mediated signaling and inducing apoptosis." (PMID 40500394, 2025). "In conclusion, we develop a novel tumor-targeted nanocarrier for the combined delivery of aPD-1 and MDK-siRNA." (PMID 40380202, 2025). "A decrease in MDK levels in xenograft tumours in mice hinders tumour growth, prolongs the survival time of mice, and enhances tumour activity by various mechanisms, including the promotion of tumour cell growth and initiation of increased cell invasion." (PMID 40468625, 2025). "Suppressing the midkine (MDK) gene via Plofsomes reduced temozolomide resistance and inhibited tumor growth in orthotopic models." (PMID 41228338, 2025). "To address ICI resistance and minimize adverse effects, we have engineered an innovative tumor-specific nanomedicine for the concurrent administration of aPD-1 and MDK-siRNA." (PMID 40380202, 2025). "Upregulated and extensive MDK expression was observed in Case 2, whereas in the other cases, it was expressed only in some parts of the tumor." (PMID 40620228, 2025). "This is further supported by recent omics-based investigations that have identified MDK as a critical molecular player in tumor aggressiveness and drug resistance." (PMID 40500394, 2025).
tumor (continued). "For example, MDK - NCL as the most prevalent ligand-receptor pair mediating communications among tumor cells." (PMID 40036264, 2025). "Tumor cells can quickly develop resistance to such inhibitors by developing alternative means to express MDK." (PMID 40429950, 2025). "Decreased MDK protein levels were maintained in resected tumors using shMDK at day 28 following tumor induction." (PMID 40620228, 2025). "Aiming at reversing immunosuppressive TME and overcoming ICB resistance for HCC immunotherapy, a dual pH-sensitive nanodrug was successfully developed to facilitate T cell-mediated and tumor-targeted delivery of both aPD-1 and MDK-siRNA." (PMID 40380202, 2025). "In hypoxic tumor microenvironments, MDK expression is induced via HIF-1α, which further contributes to epithelial-to-mesenchymal transition (EMT) and metastatic behavior." (PMID 40500394, 2025). "ANXA1 and MDK are recognized as endogenous anti-inflammatory molecules that suppress immune activity and exacerbate tumor progression." (PMID 40417666, 2025). "Spatial transcriptomics revealed nine distinct tumor niches, with MDK-NCL signaling notably upregulated at the tumor-immune interface, highlighting its role in establishing an immunosuppressive microenvironment." (PMID 40396179, 2025). "In contrast, suppression of MDK expression in the SBC5 cell line using shMDK impaired tumor cell proliferation." (PMID 40620228, 2025). "MDK also affects the tumor microenvironment, promoting lymphangiogenesis and impairing lymphatic barrier function." (PMID 40429950, 2025). "The primary tumor samples had greater MDK isoform diversity compared to primary tumor ex vivo cultures." (PMID 40835683, 2025). "Specifically, high expression of MDK in tumor cells likely engages SDC2 and NCL, both abundantly expressed on fibroblasts, to mediate these interactions." (PMID 40787466, 2025). "MDK, a molecule known for its role in leukocyte migration and tumor progression 42, has emerged as a critical mediator of epidermal self-renewal and repair." (PMID 40585982, 2025). "The findings identified Midkine (MDK) as a potential mediator of the interaction between tumor and beta cells." (PMID 40709672, 2025). "They identified MDK as a key player in facilitating tumor-promoting NF-κB signaling, macrophage recruitment, and M2 polarization, as well as suppressing a tumor-suppressive interferon (IFN) response." (PMID 40429950, 2025). "Further analysis divided tumor samples into high and low MDK-NCL expression groups based on the median enrichment score." (PMID 40396179, 2025). "This pathway upregulates midkine, an immunomodulator that alters macrophage phenotypes and contributes to immune exclusion from tumor areas." (PMID 40136353, 2025). "The pattern analysis results for EGFRvIII(−) GBM patient single-cell data revealed that in the outgoing pattern analysis, tumor cells dominated Pattern2, with the MDK signaling pathway being the most active in Pattern2." (PMID 40527884, 2025). "This study explored treatment strategies targeting EGFRvIII-mutated GBM and investigated the effects of targeted regulation of the MDK signaling pathway on tumor growth, prognosis, and the immune microenvironment in a mouse model of intracranial glioma." (PMID 40527884, 2025). "As a whole, MDK’s apparent role in modulating the tumor immune microenvironment emphasizes its potential clinical utility." (PMID 40429950, 2025). "Serum MDK concentrations in patients with SCLC reflected the SCLC tumor burden and were correlated with response to treatment." (PMID 40620228, 2025). "Collectively, these findings highlight MDK’s crucial role in tumor progression and support its potential as a therapeutic target." (PMID 40500394, 2025). "Results showed a correlation between MDK and several clinical characteristics, such as tumor number and size, vascular invasion, and clinical stage, specifically evident in mid-to-late-stage HCC." (PMID 38247828, 2024).
tumor (continued). "Cellular communication indicated the high-RMRs- expressing tumor epithelial cells had more interactions with microenvironment cells and the receptor-ligand pairs were more in the MDK and MIF signaling pathways." (PMID 39160604, 2024). "We also analyzed the ligand-receptor interactions between the different cells, and found that the S100A1+ tumor cells interacted with other cell types through the MDK-NCL receptor-ligand pair." (PMID 39742274, 2024). "Hyperactive signals sent primarily by tumour cells were identified, such as MDK, HGF, chemerin, and GDF15 signalling." (PMID 38318640, 2024). "miR-9, as a strong tumour suppressor, suppresses endothelial tube formation and migration by downregulating the MDK gene and repressing the MDK/AKT pathway." (PMID 38473281, 2024). "The model’s predictions in training and validation cohorts verified its viability, and an in vitro experiment revealed that MDK mediates the EMT of tumor cells in a hypoxic environment." (PMID 38255198, 2024). "The receivers of MDK signalling were found to involve nearly all cell types present in CM, reflecting its multiple roles in driving tumour progression." (PMID 38318640, 2024). "In SHH, Group 3 and Group 4 MBs, we identified upregulated NCAM-1 and MDK signaling as facilitators for communication between different tumor clusters." (PMID 39659836, 2024). "MDK is frequently upregulated in various human tumors and plays a crucial role in tumor development and progression." (PMID 38347596, 2024). "The intercellular communication network in CM was found to be orchestrated primarily by tumour cells, and hyperactive signals sent primarily by tumour cells were identified, such as MDK, HGF, chemerin and GDF15 signalling." (PMID 38318640, 2024). "MDK secreted by tumor epithelial cells binds to its receptor LRP1 on macrophages, promoting the infiltration of immunosuppressive macrophages." (PMID 38951896, 2024). "High midkine expression correlates with a TME that supports the presence of Tregs and tumor-associated macrophages (TAMs), both of which contribute to tumor progression and are linked to a poorer prognosis." (PMID 38629578, 2024). "The prognostic gene MDK was used for an in vitro experiment to verify the promoting effect of MDK on tumor proliferation, invasion, and metastasis in the hypoxic environment." (PMID 38255198, 2024). "NCL alters the tumour microenvironment via the midkine (MDK)‐NCL pathway, leading to the activation of cancer‐associated fibroblasts and subsequently enhancing tumour invasion." (PMID 39304978, 2024). "MDK can facilitate tumor development through activation of cancer signaling pathways mediated by receptor-ligand interactions." (PMID 38250070, 2023). "Our current study also consistently results with positive MDK expression in HNSCC patients with prompt tumor recurrence." (PMID 37743493, 2023). "The potential function of midkine were evaluated by western blot, T cell suppression assay, immunohistochemistry (IHC) staining and tumor xenograft model." (PMID 36906597, 2023). "Aside from neoplastic diseases and primary inflammatory disorders, upregulation of MDK can also be observed in injuries of peripheral organs such as the heart or the kidney." (PMID 38098484, 2023). "Both pathways counteract anti-tumor immunity, thereby implicating MDK signaling in tumor resistance." (PMID 38098484, 2023). "Both, in the periphery and the CNS, MDK elicits pro-inflammatory and anti-apoptotic effects, driving inflammation, tumor progression, and metastasis." (PMID 38098484, 2023). "Midkine-neutralizing antibodies rescued the Nf1-mutation-induced RGC hyperactivity and inhibited tumor growth in the Nf1OPG mice." (PMID 37891793, 2023). "Data from TCGA and GEO database (GSE39791 and GSE112790) also suggested that midkine was overexpressed in HCC tumor samples." (PMID 36906597, 2023).
tumor (continued). "Some studies have shown that MDK can be served to monitor the response to tumor treatment, while the secretion and overexpression of MDK in chemoresistant cells can protect themselves from cannabinoid and doxorubicin treatment 39-42." (PMID 36594100, 2023). "Treatment with antisense MDK suppresses tumorigenicity in mouse rectal carcinoma cells and other xenograft models in vitro and reduces tumor growth in nude mice in vivo." (PMID 38098484, 2023). "MDK plays a role in the multiple biological functions of cancer, such as promoting tumor cell proliferation, transformation, and epithelial-to-mesenchymal (EMT) transition." (PMID 37743493, 2023). "The study further demonstrates that Schwann cells can induce malignant progression of tumor cells and CAFs by releasing MDK and IL-1α." (PMID 37524695, 2023). "As we have discussed in this review, MDK exerts tumorigenic functions by promoting tumor growth, differentiation, and chemoresistance in neoplastic diseases." (PMID 38098484, 2023). "Altogether, our data indicated that forced midkine expression stimulated immunosuppressive MDSCs accumulation in HCC tumor microenvironment." (PMID 36906597, 2023). "As an anti-apoptotic molecule, MDK prevents the natural defense system of the cell, further increasing cell growth and promoting MDK expression in tumor tissue." (PMID 37240085, 2023). "Pleiotrophin (PTN) is a heparin-binding growth factor of the family of midkine, a tumor promoting factor." (PMID 36614248, 2023). "For instance, the use of the small molecule inhibitor iMDK, small interfering RNAs (siRNAs), or MDK blockage using anti-MDK monoclonal antibodies restores tumor apoptosis and inhibits tumor growth in mice." (PMID 38098484, 2023). "MDK is a growth factor that binds to heparin and is involved in promoting cell growth and survival in vitro and tumor growth in vivo in a model of LUAD." (PMID 38260835, 2023). "In the analysis of pathways based on L/R pairs between tumor cells and PCs, midkine (MK) and macrophage migration inhibitory factor (MIF) signaling were the most significantly enriched pathways." (PMID 37138324, 2023). "Recent studies demonstrate that blockage of MDK signaling by various approaches rescues tumor resistance." (PMID 38098484, 2023). "In the context of neoplastic diseases, increased MDK levels have been demonstrated more than 20 years ago by several studies covering various types of cancer." (PMID 38098484, 2023). "The current study focuses on MDK and IL-1α as two mediators of Schwann cells in tumor cells and CAFs." (PMID 37524695, 2023). "The data suggests that in some tumors, MDK signaling suppress CD8-mediated anti-tumor activity and blockade of the signaling reverses this effect." (PMID 36973261, 2023). "In contrast, IS tumor cells with low MDK expression showed high expression of cytokines and were enriched with immune regulatory pathways." (PMID 36028490, 2022). "CAF-secreted midkine enhances tumor cell resistance to cisplatin by inducing ANRIL expression and increasing anti-apoptotic protein Bcl-2 expression." (PMID 35978835, 2022). "cDNA microarray analysis further suggested that ACSL5 was critical to the expression of tumor-related factors including midkine (MDK), and the knockdown of MDK expression significantly attenuated ACSL5-mediated survival under an acidic state." (PMID 36507355, 2022). "Here, we uncovered that OC cells develop an adaptive strategy by upregulating midkine (MDK) to counteract the IFN-γ-induced anti-tumor activity and to fuel IFN-γ-induced metastasis." (PMID 36672515, 2022). "Surprisingly, MDK also participated in the recurrence of cSCC, and tumor tissues with the first and second recurrences had higher MDK expression levels than primary cSCC." (PMID 36438481, 2022). "MDK is highly expressed in different types of cancer and promotes tumor progression by positively regulating cell proliferation, anti-apoptosis, metastasis, angiogenesis and immune-resistance." (PMID 35487917, 2022).